RNY3P13 (RNY3 pseudogene 13)
Gene: Miscellaneous RNA gene on chromosome 3 (129,818,932 to 129,819,033, forward strand). Ensembl gene ENSG00000202412.
Homologues: Orthologues: chimpanzee Y_RNA (99% identical), macaque Y_RNA (99% identical). Paralogues in human: RNY3 (86% identical), Y_RNA (86% identical), Y_RNA (85% identical), RNY3P1 (84% identical), Y_RNA (84% identical), Y_RNA (83% identical), Y_RNA (82% identical), RNY3P2 (81% identical), Y_RNA (81% identical), RNY3P16 (80% identical), Y_RNA (80% identical), RNY3P14 (79% identical), and 94 more.